IL24 (interleukin 24)
Diseases named in the same sentence as IL24 in open-access papers (continued):
Sharing a sentence is not in itself a finding about the gene and the disease.
breast cancer (continued). "PKA stimulated phosphorylation of p38 MAPK at threonine 180 and tyrosine 182 residues in MCF‐7 breast cancer cells, leading to the upregulation of Fas, FasL, DR4, and FADD levels, all indicative of an activated extrinsic apoptotic pathway following IL‐24 treatment." (PMID 40338095, 2025). "Cotl1 is known to suppress breast cancer growth by activating the IL-24/PERP pathway and inhibiting non-canonical TGFβ signaling." (PMID 39605490, 2024). "When MCF-7 breast cancer cells are treated with IL-24, key players in the Fas signaling pathway, such as Fas, FasL, and FADD, are upregulated, supporting previous studies that IL-24 activates apoptosis extrinsically." (PMID 30424508, 2018). "Our findings, together with previous observations of MDA-7/IL-24 in promoting T-helper 1 (Th1) cytokines, suggest that an immunostimulatory effect of MDA-7/IL-24 should be exploited for effective eradication of breast cancer." (PMID 26474456, 2015). "Since most other experimental models that assessed the relevance of MDA-7/IL-24 in breast cancer did not have an intact immune system, we examined immune infiltrates in the tumors to determine the potential relevance of an intact immune system in MDA-7/IL-24-mediated tumor suppression." (PMID 26474456, 2015). "Our previous studies in breast cancer, utilizing a conditionally replication-competent adenovirus expressing mda-7/IL-24 (also known as a cancer terminator virus - CTV) showed that MDA-7/IL-24 could efficiently target primary as well as distant breast carcinomas for elimination in athymic mice." (PMID 26474456, 2015). "We observed that CNHK600-IL24 could replicate efficiently and resulted in high level IL-24 expression and massive cell death in human breast cancer cell MDA-MB-231 but not in normal fibroblast cell MRC-5." (PMID 22640485, 2012). "Thus, while the mode of action and role of MDA-7/IL-24 in mammary tumors has been well studied, the relevance of MDA-7/IL-24 in an immune competent animal is not well defined." (PMID 26474456, 2015). "To test this hypothesis, we treated several human breast cancer cell lines (MCF-7, T47D, MDA-MB-157, and MDA-MB-231) with IL-24 in the presence or absence of the specific PKA inhibitors, H-89, and PKI peptide (sequence: Myr-Gly-Arg-Thr-Gly-Arg-Arg-Asn-Ala-Ile-NH2)." (PMID 30424508, 2018).
psoriasis (38 papers, 2010 to 2025). An autoimmune condition characterized by red, well-delineated plaques with silvery scales that are usually on the extensor surfaces and scalp. "Dysregulation of IL-24 expression has been linked to several autoimmune diseases such as psoriasis, inflammatory bowel disease, and rheumatoid arthritis." (PMID 40607413, 2025). "Increased levels of IL-24 are associated with chronic autoimmune diseases, such as psoriasis, rheumatoid arthritis, and inflammatory bowel disease." (PMID 39011048, 2024). "To validate the pathogenic involvement of WNT5A+/IL24+ fibroblasts, we sought to detect these cells in other psoriasis datasets generated in the first two weeks of treatment." (PMID 38291032, 2024). "Not much is known about the function of the IL-19, IL-20, and IL-24 cytokines and their receptors, which are intrinsic to keratinocytes and are mostly associated with autoimmunity in psoriasis." (PMID 36225230, 2022). "Elevation of IL-24 is associated with chronic inflammation and autoimmune diseases, such as psoriasis, rheumatoid arthritis (RA), and inflammatory bowel disease (IBD)." (PMID 35054813, 2022). "Later studies demonstrated that IL-24 can exert proinflammatory effects and is associated with susceptibility to a number of autoimmune diseases, such as psoriasis and rheumatoid arthritis (RA)." (PMID 35054813, 2022). "Like other members of the IL-10 family, IL-24 has been shown to be upregulated in patients suffering from disorders associated with chronic inflammation, including inflammatory bowel disease and psoriasis." (PMID 30825881, 2019). "However, the elevation of IL-24 is also associated with other autoimmune diseases, including psoriasis, rheumatoid arthritis, and inflammatory bowel disease." (PMID 36233291, 2022). "Overexpression of IL-19 and IL-24 has also been observed in psoriatic skin and both induce keratinocyte hyper-proliferation in a reconstituted human skin model, suggesting a pathogenic role in psoriasis." (PMID 34616394, 2021). "Although this cytokine is involved in the process of wound healing, the overproduction of IL24 underlies pro-inflammatory autoimmune diseases such as psoriasis, allergic contact dermatitis, atopic dermatitis, rheumatoid arthritis and inflammatory bowel disease." (PMID 33139632, 2020). "IL-24 induces several psoriasis-associated factors that promote inflammation and epidermal hyperplasia, such as chemokines, pro-inflammatory cytokines, S100 family proteins, β-defensins and proteins involved in tissue remodeling, including marapsin (also known as PRSS27) and the kallikreins." (PMID 27271601, 2016). "IL-24 has anti-tumor activity and is required for optimal wound healing but also contributes to the pathogenesis of AD, psoriasis, arthritis, and inflammatory bowel diseases." (PMID 40461723, 2025). "We generate a high-resolution atlas of early disease resolution, identifying a pro-inflammatory WNT5A+/IL24+ fibroblast state that is enriched in psoriasis lesions." (PMID 38291032, 2024). "Upregulation of IL-24 is reported to be involved in wound repair and pathogenesis of inflammatory and autoimmune diseases such as psoriasis." (PMID 39364404, 2024). "Interleukin-24 (IL24), a member of the IL-20 family of cytokines, has been implicated in various autoimmune disorders, including psoriasis, arthritis, and inflammatory bowel diseases." (PMID 38792924, 2024). "The analysis of these samples confirmed that WNT5A+/IL24+ fibroblasts are only detectable in lesional psoriasis skin, where their abundance begins to decrease after one week of treatment." (PMID 38291032, 2024). "A key result from our study is the identification of a WNT5A+/IL24+ inflammatory fibroblast state, which is expanded in lesional psoriasis skin and rapidly shrinks after treatment initiation." (PMID 38291032, 2024).
psoriasis (continued). "Taken together, these observations identify the reduction of WNT5A+/IL24+ fibroblasts as an early event mediating the resolution of skin inflammation in psoriasis, following systemic or topical treatment." (PMID 38291032, 2024). "In order to gain a better knowledge of miRNAs role in the disease, the current study looked into the influence of miR-203 expression and its target genes SOCS3, SOCS6, TP63, TNF-α, IL-8, and IL-24 on the pathogenesis and clinical course of psoriasis." (PMID 36341243, 2022). "In vivo studies revealed that tumor necrosis factor (TNF)-α induces IL-24 to drive psoriasis-like skin inflammation in mice." (PMID 35054813, 2022). "This work evaluated the expression levels of the circulating miR-203 target genes SOCS3, SOCS6, TP63, TNF-, IL8, and IL24 in psoriasis patients." (PMID 36341243, 2022). "IL-20 receptor cytokines, including IL-24, are elevated in the skin lesions of patients with psoriasis, and genetic overexpression of these cytokines leads to the development of paresis-like disease in mice." (PMID 35054813, 2022). "IL-24 has been demonstrated to regulate tissue inflammation via IL-24 receptor expression in epithelial cells, such as in keratinocytes in psoriasis and colonic epithelial cells in inflammatory bowel disease." (PMID 36233291, 2022). "Significant upregulation of IL-17A, IL-19, IL-24, and Ki-67 in psoriasis was confirmed in another independent dataset." (PMID 34616394, 2021). "Interleukin-19, a member of the IL-20 subfamily together with IL-20 and IL-24, is up-regulated in psoriatic lesions and contributes to keratinocytes hyperplasia in psoriasis." (PMID 34616394, 2021). "IL-19, along with other IL-20 subfamily cytokines such as IL-20 and IL-24, is induced by IL-17A and contributes especially to epidermal hyperplasia in psoriasis." (PMID 34616394, 2021). "Following 311 nm irradiation of psoriasis, IL-24 was upregulated at 6 h and 18 h but maximally at the later time-point, consistent with previous observations in normal skin." (PMID 33812333, 2021). "In conclusion, in contrast to psoriasis where different IL-20 related cytokines play a role, IL-24 is the main IL-20-related cytokine playing a role in PPD-induced CHS, most probably via its effect on keratinocytes." (PMID 30755657, 2019). "For instance, studies on psoriasis and inflammatory bowel disease suggest a role of IL-24 in disease pathogenesis." (PMID 28301515, 2017). "Overexpression of Il20, Il22 or Il24 in mice leads to the development of psoriasis-like skin lesions, and levels of IL-19, IL-20, IL-22 and IL-24 are increased in psoriatic skin." (PMID 27799070, 2016). "It was demonstrated that skin treated with anti-TNF exhibits a downregulation of IL-24 expression in psoriasis patients, making the epidermal keratinocyte a direct target of pathogenic TNF signaling in psoriasis." (PMID 27271601, 2016). "It has been demonstrated that overexpression of IL-24 in transgenic mice lead to the development of skin lesions similar to those seen in human psoriasis." (PMID 27271601, 2016). "Various lines of evidence indicate that IL-24 plays a role in immune-pathological diseases, including psoriasis, rheumatoid arthritis, and inflammatory bowel disease (IBD)." (PMID 27271601, 2016). "In some respects, the strongest evidence from our study supports the IL-20 family cytokines as drivers of differential gene expression in psoriasis (i.e., IL-19, IL-20 and IL-24)." (PMID 23915137, 2013). "IL-24 expression is increased in inflammatory skin disease like AD or psoriasis and IL-24 induces, as well as the other IL-10 family members IL-19 and IL-20, the proliferation of keratinocytes in 2D cultures." (PMID 23531535, 2013). "Taken together these findings suggest a role for IL-24 in the pathogenesis of psoriasis and other inflammatory conditions." (PMID 20072629, 2010).
psoriasis (continued). "Increased expression of IL-24 has been reported in affected joints of patients with rheumatoid arthritis and in lesional skin of patients with psoriasis." (PMID 20072629, 2010). "In addition, IL-24 has been described as a novel player in the pathogenesis of allergic skin inflammation, including psoriasis, arthritis, inflammatory bowel disease, and atopic dermatitis (AD)." (PMID 41394797, 2025). "We hypothesize that an increased release of R7 from the differentiated keratinocytes of AD and psoriasis patients fosters the secretion of IL-6 and IL-24, especially from the undifferentiated keratinocytes of the stratum basale." (PMID 40461723, 2025). "Both WNT5A and IL24 are overexpressed in psoriasis skin lesions." (PMID 38291032, 2024). "To understand whether WNT5A+/IL24+ fibroblasts are present in other inflammatory skin diseases beyond psoriasis, we sought to detect these cells in publicly available scRNA-seq datasets." (PMID 38291032, 2024). "Likewise, the analysis of future datasets of treatment responses will establish if WNT5A+/IL24+ fibroblasts undergo dynamic, treatment-dependent shifts in other inflammatory skin diseases beyond psoriasis." (PMID 38291032, 2024). "In addition, IL-24 overexpression in psoriasis prompts the expression of pro-inflammatory chemokines CXCL1, CXCL8, and CCL20." (PMID 34638757, 2021). "Furthermore, transgenic mice overexpressing IL-24 have been shown to develop psoriasis-like skin lesions, exhibiting thickening of the epidermis and monocyte infiltration." (PMID 30825881, 2019). "In line with this, single-nucleotide polymorphisms of the IL-19 gene (but not the IL-20 or IL-24 genes) are protective in psoriasis." (PMID 30319661, 2018). "In psoriasis, Compound 5c reduced IL-6, IL-8, IL-1β and IL-24 in imiquimod-stimulated models." (PMID 30301277, 2018). "Anti-psoriasis mechanism studies have indicated that compound 5c reduced the secretion of IL-1β, IL-6, IL-8 and IL-24 in an IMQ-stimulated model and could also attenuate the activation of IMQ-induced MAPKs, including JNK1/2 and ERK1/2." (PMID 30301277, 2018). "It has been reported that the cytokines IL-19, IL-20 and IL-24 are highly expressed in the inflammatory sites of psoriasis, and may thus mediate the progression of psoriasis." (PMID 22792286, 2012). "If this finding is confirmed in future cohorts, the frequency of WNT5A+/IL24+ cells could be monitored in the increasing number of patients receiving biologics, with the potential to inform personalized, drug tapering strategies in psoriasis remission." (PMID 38291032, 2024). "Furthermore, IL-24 from activated T cell-derived microvesicles motivated MCs and excessive MCs activation in psoriasis could produce IL-24, subsequently provoking STAT3 phosphorylation of KCs." (PMID 36242051, 2022). "Furthermore, both TNF-α and IL-6 can induce IL-24 production in psoriasis." (PMID 34638757, 2021). "In addition to keratinocytes, dermal fibroblasts, through interaction with immune cells and cytokines such as IL-17A and TNF in psoriasis, can be a major source of IL-19 and IL-24 that contribute to perpetuation of psoriatic symptoms such as keratinocyte proliferation and acanthosis." (PMID 34616394, 2021). "IL24 has also been found in many diseases involving inflammation, such as cardiovascular disease, rheumatoid arthritis, tuberculosis, and viral infections, and may play a role in psoriasis." (PMID 33014054, 2020). "Altogether, the studies of psoriasis and IL-24 support the idea that IL-24 plays a significant role in the expression of pro-inflammatory mediators resulting in psoriatic skin lesions thus, providing evidence that IL-24 is a key factor in the initiation of psoriasis." (PMID 27271601, 2016). "Taken together, our observations identify WNT5A+/IL24+ fibroblasts as an IL-17/TNF dependent, inflammatory cell state, that in psoriasis, is rapidly normalized by IL-23 blockade." (PMID 38291032, 2024).
psoriasis (continued). "Interestingly, a closer inspection of single-cell profiles identified some differences between prurigo nodularis and psoriasis lesions, with WNT5A+/IL24+ fibroblasts expressing TBX3 and CXCL8 only in the latter." (PMID 38291032, 2024). "We conducted this study to evaluate miR-203 expression level in the plasma of psoriasis patients to investigate its role and target genes SOCS3, SOCS6, P63, TNF-α, IL-8, and IL-24 in the systemic pathogenesis of this disease and correlate these data with the disease course." (PMID 36341243, 2022). "Furthermore, the ELISA data showed that the pro-inflammatory mediators including IL-6, IL-17A, IL-23, IL-24, and TNF dramatically increased in psoriasis-like mice intervened by shLuc." (PMID 34638757, 2021). "IL-24 is a member of the IL-20 family induced by IL-6, TNF, and IL-1β in psoriasis." (PMID 34054833, 2021). "Data from mice suggests that this elevation can augment epidermal hyperplasia, since overexpression of either IL-20 or IL-24 (but not IL-19) elicits a psoriasis-like phenotype." (PMID 23915137, 2013). "Furthermore, IL-24 stimulation of NHEK resulted in altered keratinocyte differentiation pattern, increased cell proliferation, and expression of a number of psoriasis-related genes." (PMID 20072629, 2010). "The exact role of IL-24 in the immune system has not been defined but studies have indicated a role for IL-24 in inflammatory conditions such as psoriasis." (PMID 20072629, 2010). "Thus, the increased expression of IL-24 mRNA in lesional psoriatic skin corresponds nicely with the increased activation of p38 MAPK in psoriasis and indicates a role for IL-24 in the pathogenesis of psoriasis." (PMID 20072629, 2010). "This indicates that IL-19 and IL-24, rather than IL-22, IL-17A or IL-17F, were responsible for the late stage (day 10) keratinocyte hyper-proliferation and acanthosis in the IMQ-induced psoriasis mouse model during anti-IL-10 treatment." (PMID 34616394, 2021).
prostate carcinoma (36 papers, 2011 to 2025). A carcinoma that arises from epithelial cells of the prostate gland. "In summary, we have discovered in our present study that while ILs-3, 6 and 11 have similar tumor promotion and stemness stimulation effects, IL-10 and IL-24 reveal opposite effects on prostate cancer cells in vitro, underlining a complex role of ILs in vivo, which merit further studies." (PMID 26528857, 2015). "The requirement for GSK3β phosphorylation in serine 9 for IL-24-induced apoptosis was analyzed by IL-24 treatment of human prostate cancer cell lines expressing constitutively active GSK3β." (PMID 40072085, 2025). "Our studies show for the first time that GSK3β is inhibited following IL-24 treatment in human prostate cancer cells." (PMID 40072085, 2025). "The present study defines the pro-apoptotic mechanism by which IL-24 promoted the death of human prostate cancer cells." (PMID 40072085, 2025). "While in most cancer cells transfection using replication‐incompetent adenovirus overexpressing IL‐24 led to expression of IL‐24, prostate cancer cells remained an exception." (PMID 40338095, 2025). "Subsequent research should aim to precisely delineate the most effective combinations of IL-24 as a GSK3β inhibitor with cytotoxic agents in different cancers, including prostate cancer cells." (PMID 40072085, 2025). "The findings of this study uncover a novel mechanism of IL-24 in apoptosis mediated through cAMP/PKA/GSK3β regulation in prostate cancer cells." (PMID 40072085, 2025). "We treated DU145 human prostate cancer cells with increasing concentrations of IL-24 for 72 h and analyzed the activity and phosphorylation of serine 9 of GSK3β." (PMID 40072085, 2025). "Our findings demonstrate for the first time that IL-24 exerts its pro-apoptotic effects in human prostate cancer cells by activating the PKA pathway and subsequently inhibiting GSK3β." (PMID 40072085, 2025). "Another research team showed selective induction of cell cycle arrest and apoptosis in human prostate cancer cells through adenoviral transfer of Mda-7/interleukin-24 (IL-24)." (PMID 37280571, 2023). "Recombinant interleukin-24 (IL24) is potentially a novel therapeutic for preventing bone metastasis since IL24 suppressed colonization of CRPC cells to bone in a mouse prostate cancer metastasis model." (PMID 35205640, 2022). "Hi-Myc transgenic mice that spontaneously develop prostate cancer were also used to evaluate the therapeutic potency of human MDA-7/IL-24-producing T cells." (PMID 35008495, 2021). "Histological analysis of prostate tissues showed that treatment with MDA-7/IL-24-producing T cells significantly reduced progression of prostate cancer." (PMID 35008495, 2021). "MDA-7/IL-24 also acted synergistically in colorectal cancer and prostate cancer cells when combined with the Apogossypol derivatives, BI-97C1 and BI-97D6, which are pharmacological inhibitors of Mcl-1." (PMID 35008495, 2021). "The improved transgene delivery and efficacy of an Ad.5/3 recombinant virus expressing mda-7/IL-24, has been demonstrated in prostate cancer, glioma, colorectal, and renal cancer." (PMID 35008495, 2021). "In combination with treatments such as ionizing radiation and Sabutoclax, IL-24 can also sensitize prostate cancer tumors to apoptosis." (PMID 30669553, 2019). "Along with killing other cancer cell types, IL-24 induces apoptosis in prostate cancer cells through endoplasmic reticulum (ER) stress, mitochondrial dysfunction, reactive oxygen species accumulation, and downregulation of anti-apoptotic proteins." (PMID 30669553, 2019). "MiR-205 is down-regulated in prostate cancer, and its restoration reduces cell proliferation by activating the interleukin 24 and interleukin 32 (IL24 and IL32) genes." (PMID 29401683, 2018). "We have previously shown that the Mcl-1 antagonist Sabutoclax alone or in combination with the tumor suppressor mda-7/IL-24 induces cancer-specific cell death in human prostate carcinomas (PC)." (PMID 26009874, 2015).